SYPL1 (synaptophysin like 1)
Synonyms: SYPL; H-SP1
Tractability: Antibody: its Gene Ontology location is reachable by antibodies, with high confidence; UniProt predicts a signal peptide or a membrane-spanning region. PROTAC: ubiquitination databases record sites on it; its protein half-life has been measured.
Gene: Protein-coding gene on chromosome 7 (106,090,500 to 106,112,589, reverse strand). Ensembl gene ENSG00000008282.
Subcellular location: Cytoplasmic vesicle membrane; Melanosome
Gene Ontology:
Molecular function: protein binding
Biological process: chemical synaptic transmission
Cellular component: extracellular exosome; membrane; plasma membrane; synaptic vesicle membrane; cytoplasmic vesicle membrane; melanosome; secretory granule; synaptic vesicle
Genetic constraint (gnomAD): Loss-of-function variants: 6 observed, 21.76 expected, observed/expected ratio (o/e) 0.28, 90% interval 0.15 to 0.54. The upper end of that interval is the gene's LOEUF score, 0.54, which puts it in group 2 of 6, group 1 being the genes least tolerant of losing a copy. Missense variants: 253 observed, 289.33 expected, observed/expected ratio (o/e) 0.87, 90% interval 0.79 to 0.97. Synonymous variants: 102 observed, 105.06 expected, observed/expected ratio (o/e) 0.97, 90% interval 0.83 to 1.14.
Homologues: Orthologues: chimpanzee SYPL1 (99% identical), macaque SYPL1 (96% identical), dog SYPL1 (87% identical), pig SYPL1 (85% identical), mouse Sypl1 (84% identical), guinea pig SYPL1 (81% identical), rat Sypl1 (78% identical), tropical clawed frog sypl1 (48% identical), zebrafish sypl1 (47% identical), Caenorhabditis elegans sph-1 (23% identical). Paralogues in human: SYNPR (46% identical), SYP (43% identical), SYPL2 (38% identical).
Diseases named in the same sentence as SYPL1 in open-access papers:
SYPL1 is named in the same sentence as 32 diseases in open-access papers, as found by Europe PMC text mining. Sharing a sentence is not in itself a finding about the gene and the disease. The quoted sentences say what the papers report.
colorectal cancer (4 papers, 2009 to 2024). A primary or metastatic malignant neoplasm that affects the colon or rectum. "SYPL1 encodes synaptophysin-like 1 (SYPL1), a protein that has emerged as a prognostic marker and potential target in pancreatic ductal adenocarcinoma, hepatocellular carcinoma, and colorectal cancer." (PMID 38347462, 2024). "Synaptophysin like 1 (SYPL1) is a synaptic vesicle membrane protein that participates in cancer development such as colorectal cancer (CRC) and papillary thyroid carcinoma, and can serve as a biomarker for disease diagnosis." (PMID 35778739, 2022). "In addition, a statistically significant relationship was found with lymph node invasion, and they showed that SYPL1 level decreased in patients who underwent radical surgery for colorectal cancer." (PMID 38699696, 2024).
hepatocellular carcinoma (4 papers, 2022 to 2025). A malignant tumor that arises from hepatocytes. "Clinically, SYPL1 expression is characterized with an increase in hepatocellular carcinoma, unfortunately resulting in miserable overall survival and disease-free survival." (PMID 35778739, 2022). "Overexpressed SYPL1 was closely tied up with malignant clinicopathological features in hepatocellular carcinoma." (PMID 35778739, 2022). "SYPL1 plays a vital role in colorectal cancer (CRC), PDAC, hepatocellular carcinoma (HCC), breast cancer (BC), and papillary thyroid carcinoma (PTC)." (PMID 40507479, 2025).
breast cancer (3 papers, 2021 to 2025). A primary or metastatic malignant neoplasm involving the breast. "However, due to its low sensitivity, SYPL1 alone is insufficient for diagnosing breast cancer." (PMID 38699696, 2024). "However, one of the strengths of our study is that, to the best of our knowledge, the serum SYPL1 protein has not been previously investigated in breast cancer patients." (PMID 38699696, 2024).
pancreatic ductal adenocarcinoma (3 papers, 2020 to 2025). An infiltrating adenocarcinoma that arises from the epithelial cells of the pancreas. "The role of SYPL1 in pancreatic ductal adenocarcinoma (PDAC) and the underlying molecular mechanism remain unclarified." (PMID 33042794, 2020).
male infertility (1 paper, 2023). The inability of the male to effect fertilization of an ovum after a specified period of unprotected intercourse. "Thus, the male infertility of Sypl1 KO mice could be caused by a combination of motility and morphological defects." (PMID 37607933, 2023).
Obesity (1 paper, 2021). Accumulation of substantial excess body fat. "A homozygous missense variant [p.(Cys51Tyr)] in SYPL1 (OMIM # 616,665), was found in FIN21-3 whose phenotype characterized by metopic ridge and delayed bone maturation (-4.5SD), mild ID, panic disorder, and obesity [body-mass index (BMI = 36)]." (PMID 33710394, 2021).
oral squamous cell carcinoma (1 paper, 2022). "Ying Yang1 (YY1) has already been discussed in oral squamous cell carcinoma (OSCC), but the knowledge about its mediation on long non-coding RNA KCNQ1 overlapping transcript 1/microRNA-506-3p/synaptophysin like 1 (Kcnq1ot/miR-506-3p/SYPL1) axis in OSCC is still in its infancy." (PMID 35778739, 2022).
pancreatic adenocarcinoma (1 paper, 2020). "To explore the regulatory mechanisms of SYPL1, we searched for genes closely correlated with SYPL1 in pancreatic adenocarcinoma datasets of GEPIA." (PMID 33042794, 2020).
pancreatic cancer (1 paper, 2025). "Therefore, SYPL1 shows promise as a non-invasive biomarker for tracking the clinical course of pancreatic cancer and evaluating treatment effectiveness." (PMID 40507479, 2025).
renal failure (1 paper, 2024). "We thinkthat the serum SYPL1 level may change in the case of renal failure." (PMID 38699696, 2024).
cancer (6 papers, 2019 to 2025). A tumor composed of atypical neoplastic, often pleomorphic cells that invade other tissues. "Further research is needed to elucidate the precise molecular mechanisms underlying SYPL1’s involvement in cancer progression and its potential therapeutic applications." (PMID 40507479, 2025). "The fact that SYPL1 is present in both serum and fecal samples suggests its potential for non-invasive diagnostic applications, making it a valuable tool for early cancer detection and population screening." (PMID 40507479, 2025). "Data analysis based on five datasets (GSE15471, GSE16515, GSE28735, TCGA, and PACA-AU) shows that SYPL1 is associated with the proliferation and survival of cancer cells." (PMID 33042794, 2020). "Elevated SYPL1 expression is associated with poor prognosis, while its downregulation—either directly or via circ_0004104 knockdown—suppresses tumor growth, suggesting SYPL1 may serve as a potential marker for cancer progression and treatment response in CRC." (PMID 40507479, 2025). "The most important finding of this study is that SYPL-1 levels were significantly elevated in both cancer groups, with the highest levels in mPDAC patients, compared to rPDAC and controls." (PMID 40507479, 2025). "Overall, SYPL1 shows significant promise in oncology, especially for early detection and monitoring of cancer progression." (PMID 40507479, 2025). "Overall, SYPL1 appears to influence cancer development through anti-apoptotic signaling, inflammation, EMT regulation, and intracellular trafficking, though further studies are needed to fully define its tumor-specific roles." (PMID 40507479, 2025). "From all of the listed reports, it is easy to abstract that the manifestations of these four factors (YY1, Kcnq1ot1, miR-506-3p and SYPL1) in the malignant phenotypes of cancers are consonant with the findings in the present work." (PMID 35778739, 2022). "In general, YY1, Kcnq1ot1, miR-506-3p and SYPL1 have the applicable prospects in treating cancers, but the mechanism focused on their loop feedback in OSCC was rarely elaborated." (PMID 35778739, 2022). "While the precise molecular mechanisms of SYPL-1 in cancer remain under investigation, recent studies suggest that SYPL-1 may contribute to tumorigenesis by regulating cell proliferation, vesicle trafficking, and membrane dynamics." (PMID 40507479, 2025). "Its significantly elevated levels in cancer groups, coupled with its marked decrease following surgical resection, suggest that SYPL-1 could play a critical role in both initial diagnosis and post-treatment surveillance." (PMID 40507479, 2025). "Given these capabilities, SYPL1 could become a key marker in the management of cancer, aiding not only in diagnosis but also in predicting outcomes and guiding therapeutic strategies." (PMID 40507479, 2025). "Serum SYPL1 is a promising biomarker for many cancers, including PC." (PMID 40507479, 2025). "Abnormalities in YY1, Kcnq1ot1, miR-506-3p, and SYPL1 have been manifested in cancer progression." (PMID 35778739, 2022).
tumor (5 papers, 2020 to 2025). "In PDAC, SYPL-1 overexpression has been associated with enhanced tumor cell growth and poor prognosis." (PMID 40507479, 2025). "Notably, SYPL1 has been implicated in regulating the NF-κB signaling pathway, which plays a central role in inflammation, tumor proliferation, and progression." (PMID 40507479, 2025). "In HCC, SYPL1 overexpression is associated with poor prognosis and may promote tumor proliferation and invasion through EMT." (PMID 40507479, 2025). "The present study demonstrates that SYPL1, which is upregulated in tumor tissue and PDAC cell lines at the transcriptional level and protein level, is an independent factor associated with poor prognosis." (PMID 33042794, 2020). "In this study, significant upregulation of SYPL1 was detected in PDAC patient tumor tissue, which indicated poor prognosis." (PMID 33042794, 2020). "Through CCK-8, colony formation and subcutaneous xenotransplanted tumor models in nude mice, we found that downregulation of SYPL1 inhibits tumor growth in vitro and in vivo, while overexpressed SYPL1 promotes cell proliferation." (PMID 33042794, 2020). "Furthermore, when examining the correlation analyses, SYPL-1 appears to exhibit a distinct pattern compared to traditional tumor markers, such as CA19-9 and CEA." (PMID 40507479, 2025). "This suggests that SYPL1 may play a crucial role in the aggressive nature of PDAC by promoting tumor growth and proliferation." (PMID 40507479, 2025). "Data analysis and flow cytometry show that SYPL1 protects tumor cells from apoptosis." (PMID 33042794, 2020). "Knockdown of SYPL1 inhibited proliferation, induced apoptosis of tumor cells, and vice versa." (PMID 33042794, 2020). "SYPL1 was elevated in tumor tissue at the level of transcription." (PMID 33042794, 2020). "Knockdown of SYPL1 in tumor cells slowed the growth of tumors." (PMID 33042794, 2020). "Additionally, the ability of SYPL1 to support cell proliferation suggests that it could be involved in mechanisms that drive tumor progression, making it a potential target for future therapeutic strategies." (PMID 40507479, 2025). "Besides, in TCGA dataset, SYPL1 positively correlated with tumor size." (PMID 33042794, 2020). "SYPL-1 contributes to PDAC progression by inhibiting apoptosis through the suppression of ROS-induced ERK activation, thereby promoting tumor cell survival." (PMID 40507479, 2025). "In this study, we aimed to investigate the relationship between serum levels of synaptophysin-like protein 1 (SYPL1) and BC and compare SYPL1 with other blood tumor markers." (PMID 38699696, 2024). "However, in IHC, the expression of SYPL1 did not correlate with the tumor sizes of patients in SYSUCC, which may result from insufficient sample size and sampling error." (PMID 33042794, 2020). "Notably, SYPL-1 showed a negative correlation with CEA in the mPDAC group, suggesting it may be associated with a different biological pathway or mechanism involved in tumor behavior or progression." (PMID 40507479, 2025).
infection (1 paper, 2022). The state of being infected such as from the introduction of a foreign agent such as serum, vaccine, antigenic substance or organism. "The proinflammatory chemokines CCL3, CXCL3, and CXCL10 were also upregulated following infection, while synapse-related genes, including C1QL1 and SYPL1, were downregulated." (PMID 36314791, 2022).
SYPL1 also shares sentences with these, for which no sentence is quoted: adenoma (2 papers); colon cancer (2); paranoid schizophrenia (2); acute myeloid leukaemia (1); albinism (1); astrocytoma (1); Canavan disease (1); fibrosarcoma (1); Gorlin syndrome (1); MELAS syndrome (1); metabolic syndrome (1); metastatic disease (1); panic disorder (1); papillary thyroid carcinoma (1); Pythiosis (1); sarcoma (1); small cell lung carcinoma (1); spindle cell sarcoma (1); sterility (1).